IGF1R (insulin like growth factor 1 receptor)
Diseases named in the same sentence as IGF1R in open-access papers (continued):
Sharing a sentence is not in itself a finding about the gene and the disease.
osteosarcoma (123 papers, 2003 to 2025). A usually aggressive malignant bone-forming mesenchymal neoplasm, predominantly affecting adolescents and young adults. "Using concurrent genomic platforms profiling on a substantial number of osteosarcoma samples, we were able to establish a correlation between IGF1R copy number and expression and an association with survival." (PMID 35887382, 2022). "For example; The high proliferative activity of cells of the human osteosarcoma cell line HOS 58 was shown to be associated with increased IGF-1R expression, indicating the regulatory role of the IGF axis in bone cancer proliferation and differentiation." (PMID 36713521, 2022). "Amplification of the IGF1R gene, and its association with oncogenesis and cell survival, has been discovered in subsets of osteosarcoma, a percentage of breast tumors, melanoma, pancreatic adenocarcinoma and gastrointestinal stromal tumors." (PMID 34440844, 2021). "Increased IGF1/IGF1R expression has been demostrated in osteosarcoma patients’ tissues and it was associated with a poor prognosis." (PMID 34440844, 2021). "IGF-1R is another tyrosine receptor kinase that has been linked to osteosarcoma pathogenesis, and enhanced tumorigenesis in human and canine cell lines." (PMID 32961800, 2020). "In the canine osteosarcoma, IGF-1R mRNA and protein expression are strictly associated with surgical stage and distant metastasis." (PMID 30881341, 2019). "Some of these genes, or the pathways they regulate, including the PVT1/MYC locus, MET signaling, and IGF1R have been implicated in genetically engineered mouse models of osteosarcoma." (PMID 29056713, 2016). "Moreover, a recent study showed that expression of IGF1R in canine osteosarcoma is associated with a poorer prognosis." (PMID 36768202, 2023). "However, in osteosarcoma, the IGF-1R/mTOR pathway has been implicated as a driver of anti-apoptotic signals and aberrant growth in many cancers making the pathway an attractive target for potential therapies." (PMID 35284040, 2022). "Indeed, 7–14% of osteosarcoma cases exhibit mutations in IGF signaling genes (IGF1R, IGF1, IGF2R, and IGFBP5)." (PMID 34069554, 2021). "Furthermore, an exclusive nuclear localization of IGF-1R was associated with progression-free survival and overall survival in osteosarcoma patients treated with IGF-1R Ab therapy." (PMID 34069554, 2021). "Loss of lncRNA SNHG12 could reverse IGF1R-triggered osteosarcoma progression by targeting miR-195-5p." (PMID 32492657, 2020). "Higher IGF-1R expression in osteosarcoma patients is associated with poorer survival." (PMID 32984034, 2020). "In addition, IGF-1 and IGF1R have been implicated in other canine cancers including osteosarcoma, malignant melanoma and testis tumors, suggesting a major role of the IGF system in canine oncology." (PMID 26449867, 2015). "Preclinical studies demonstrate anti-IGF1R antibodies inhibit tumor cell growth in xenograft models of osteosarcoma, however, mutations in the IGF1R gene and changes in expression of IGF1R do not appear to be the driving force behind response to anti-IGF1R antibody therapy." (PMID 25170759, 2014). "The insulin-like growth factor 1 receptor (IGF-1R) is frequently overexpressed in osteosarcoma, contributing to enhanced cell proliferation and survival through the activation of downstream signaling pathways, including the PI3K/Akt and MAPK pathways." (PMID 40283955, 2025). "Current research findings indicate that circRNAs can modulate the sensitivity of chemotherapy drugs in some tumors, such as in osteosarcoma, where they can promote progression and regulate cisplatin sensitivity through the miR-339-3p/IGF1R axis." (PMID 39967686, 2025). "The molecular landscape of osteosarcoma is complex, with receptor tyrosine kinases (RTKs) such as IGF-1R, PDGFR, and HER2 playing pivotal roles in tumor growth and progression." (PMID 40283955, 2025).
osteosarcoma (continued). "It is also to note that CAR T-cells engineered to target the IGF1R protein expressed at the surface of tumor cells have been developed and demonstrated to be effective in osteosarcoma xenograft models." (PMID 38420122, 2024). "For rhabdomyosarcoma, osteosarcoma, and neuroblastoma, responses to anti-IGF1R MABs have been uncommon, although prolonged stable disease has been observed in some patients." (PMID 39510293, 2024). "It has been reported that CircDOCK1 promotes the tumorigenesis and cisplatin resistance of osteogenic sarcoma via the miR-339-3p/IGF1R axis." (PMID 37993925, 2023). "It was reported that insulin induced EMT of mammary epithelial cells, while blocking insulin-like growth factor (IGF)/insulin-like growth factor-1 factor (IGF1R) signaling axis suppressed EMT of osteosarcoma cells." (PMID 37386367, 2023). "MicroRNA-939-5p directly targets IGF-1R and suppresses the aggressive phenotype of osteosarcoma by inactivating the PI3K/Akt pathway." (PMID 36090902, 2022). "The IGF-1R/PI3K/mTOR cascade has been the subject of clinical trials in osteosarcoma with variable success." (PMID 35284040, 2022). "Accordingly, blockage of IGF-1R caused down-regulation of matrix metalloproteinase-2 (MMP-2) and MMP-9 and suppress migration of human osteosarcoma (OS) MG-63 cells." (PMID 36713521, 2022). "In support of our data, the elevated level of IGF-1R mRNA and protein in osteosarcoma tissue and its correlation with tumor stage and distant metastasis was reported." (PMID 36713521, 2022). "In this work, we probed TMAs of core biopsies of osteosarcoma in patients with known outcomes to investigate the relationship between nuclear IGF-1R localization/activation and YAP/TAZ nuclear to cytoplasmic ratios." (PMID 35284040, 2022). "The analysis of the expression pattern in 59 osteosarcomas showed that IGF1R expression is highly correlated with ABCG2 expression and with CD44 expression in osteosarcoma patients under 10 years old." (PMID 35785191, 2022). "Both statistical models corroborated previous studies that implicate IGF-1R/mTOR in aggressive osteosarcoma." (PMID 35284040, 2022). "Early studies have shown that blocking the IGF/IGF-1R signal axis with soluble IGF-1R mutants can inhibit the cell proliferation and tumor growth of human osteosarcoma." (PMID 36387908, 2022). "This is consistent with previous reports that implicate increased activity of IGF1R signaling in high-grade osteosarcoma, and that treatment with IGF1R inhibitors can successfully reduce proliferation of osteosarcoma cell lines." (PMID 35887382, 2022). "The lncRNA LINC00319 separately promotes the progression of cervical cancer via regulating the miR-147a/IGF1R axis and the osteosarcoma progression via sponging miR-455-3p to regulate NFIB." (PMID 35675043, 2022). "Osteosarcoma is a high-grade sarcoma characterized by osteoid formation, nearly universal expression of IGF1R and with a subset expressing HER-2." (PMID 36457575, 2022). "Specifically, biglycan favors MG63 osteosarcoma cell proliferation via a LPR6/β-catenin/IGF-1R signaling axis and functions in a positive feedback loop regulating osteosarcoma growth." (PMID 34917515, 2021). "Deregulation of IGF1R expression on the other hand can contribute to cancer progression and has been described in osteosarcoma previously." (PMID 33295144, 2021). "The authors demonstrated that NNT-AS1 acted by sponging miR-320a thereby increasing the expression of osteosarcoma-promoting genes including IGF1R." (PMID 34484116, 2021). "Since IGF-1R mediated signaling also seems to have an oncogenic effect in osteosarcomas, monoclonalanti-IGF-1R antibodies have been developed." (PMID 33917001, 2021).
osteosarcoma (continued). "In veterinary medicine, treating cells with IGF-1 was shown to increase invasiveness in just one of three osteosarcoma cell lines (with high insulin-like growth factor receptor 1 (IGF1-R) expression)." (PMID 33807419, 2021). "In nude mice, the silencing of this lncRNA reduced tumor weight and volume, and functional analysis showed that lncSNHG12 downregulation suppressed osteosarcoma cell growth via the regulation of the miR-195-5p/IGF1R axis." (PMID 34484116, 2021). "Consistently, IGF1R protein levels were increased in osteosarcoma cells overexpressing NNT-AS1, while it was decreased after NNT-AS1 knockdown." (PMID 34484116, 2021). "In this study, we screened a large set of osteosarcomas and found specific CN gains of the IGF1R gene in 18 of 253 (7.1%) cases with corresponding IGF1R overexpression." (PMID 33295144, 2021). "Another study demonstrated that Cyr61 enhanced metastatic progression of osteosarcoma by stimulating the expression of the IGF1R, thus evoking EMT." (PMID 34440844, 2021). "Studies have shown that AFAP1-AS1 expression is increased, and its knockdown inhibits osteosarcoma progression by regulating miR-497/IGF1R." (PMID 34335760, 2021). "Other events have been reported to govern IGF1R expression in osteosarcoma, further demonstrating the complexity which surrounds the IGF axis in this tumor." (PMID 34440844, 2021). "Partial responses were registered in 3/24 (12.5%) osteosarcoma cases treated with a combination of anti-IGF1R mAb cixutumumab and the mTOR inhibitor tensirolibus." (PMID 34440844, 2021). "Consistently, an inverse correlation between miR-503 and IGF1R levels was identified in osteosarcoma tissues." (PMID 34484116, 2021). "In spite of all this evidence Benini and colleagues showed that treatment of osteosarcoma cell lines with the anti-IGF1R antibody αIR3 was ineffective as single therapy." (PMID 34440844, 2021). "Bioinformatic analysis identified IGF1R as a putative target for miR-939, which was further confirmed via luciferase assay in cell lines and supported by the observation of an inverse correlation between miR-939 and IGF1R levels in osteosarcoma tissues." (PMID 34484116, 2021). "The results of the study of Zhang indicated that let-7b suppressed proliferation and invasion of osteosarcoma cells via targeting IGF1R." (PMID 35111808, 2021). "Increased expression of IGF-1 and IGF-1R have been reported in the majority of sarcomas, including osteosarcoma, EWS, and soft tissue sarcomas, and has been correlated with disease progression." (PMID 34069554, 2021). "Combining all results obtained by DNA sequencing, RNA sequencing and FISH, we conclude that IGF1R CN gain affected 18/253 osteosarcomas (7.1%)." (PMID 33295144, 2021). "IGF-1 and IGF-1R push osteosarcoma progression through subsequent malignant transformation, proliferation, attenuated susceptibility to apoptosis, and the differentiation of a prone to metastasis phenotype." (PMID 34069554, 2021). "In particular, lncSNHG12 downregulation reversed IGF1R-induced metastases and proliferation in osteosarcoma cells." (PMID 34484116, 2021). "All these studies highlight that IGF1R is a common target of most of the miRNAs studied in the context of osteosarcoma and this confirms also the complexity of the miRNA network in the regulation of gene expression." (PMID 34484116, 2021). "In the largest sequencing study of osteosarcoma so far, 8 of 112 patients with osteosarcoma (7%) presented with high copy gains of IGF1R using whole exome sequencing data." (PMID 33295144, 2021). "Extensive screening and validation strategies identified IGF-1R as one of the specific RTKs that can activated and promote the phenotype of osteosarcoma cells in vitro." (PMID 32984034, 2020). "PPP has been shown to suppress the proliferation of osteosarcoma cell lines by inhibiting the IGF1R pathway and to reverse their drug-resistant phenotype." (PMID 32224911, 2020).
osteosarcoma (continued). "Another molecule with tyrosine kinase activity, IGF-1R, has been found to be highly expressed in osteosarcoma, and this high expression has been correlated with metastatic disease and poor overall survival." (PMID 32961800, 2020). "One study found that blocking IGF-1R by the compound tyrphostin (AG1024) together with doxorubicin enhanced growth inhibition in osteosarcoma cell lines more than either compound alone." (PMID 32961800, 2020). "Regarding osteosarcoma, a study showed that the relative expression of IGF-1R in osteosarcoma was significantly higher than that in corresponding non-cancerous bones." (PMID 32984034, 2020). "A monoclonal antibody against IGF-1R (R1507) was able to restrict growth in osteosarcoma xenograft tumours alone and in the presence of the mTOR inhibitor rapamycin, but did not have a clinical effect in a phase II clinical trial." (PMID 32961800, 2020). "In a phase II trial of the IGF-1R monoclonal antibody R1507 in patients with osteosarcoma, only two PRs were observed in 38 patients, with median PFS of 5.7 weeks." (PMID 32984034, 2020). "Robatumumab, a fully human neutralizing anti-IGF-1R antibody, was tested in a phase II study of patients with relapsed osteosarcoma or Ewing sarcoma." (PMID 32961800, 2020). "This is in accordance with the correlation mentioned between elevated IGF1R mRNA expression and distant metastasis occurrence in human osteosarcoma tumor." (PMID 30642298, 2019). "Some clinical trials focusing on monoclonal anti-IGF1R in patients with relapsed and/or recurrent osteosarcoma are ongoing." (PMID 30642298, 2019). "In osteosarcoma cells, miR-302a inhibits cell migration and invasion by directly targeting IGF-1R, and miR-302a can target GAB2, CXCR4, SDF1, Cyclin A, and Cyclin D to suppress cell proliferation, migration and invasion in glioma." (PMID 30765768, 2019). "Phase-I and phase-II clinical trials evaluating IGF-1R antibodies as therapy for osteosarcoma patients have returned mixed results." (PMID 30642298, 2019). "miR-217 was suggested to be a tumor suppressor by targeting Wnt5a in osteosarcoma and targeting IGF1R in ovarian cancer." (PMID 28437471, 2017). "Given this prior interest, we assessed IGF1R copy number in an extension cohort of 87 cases of childhood and adult osteosarcoma." (PMID 28643781, 2017). "We have been able to dissect some of the diversity of osteosarcoma by identifying a subgroup of tumours driven by potentially actionable alterations in IGF1R signalling and by defining distinct patterns of rearrangement." (PMID 28643781, 2017). "The insulin growth factor-I receptor (IGF1R) signaling is a key mechanism for osteosarcoma (OS) cell proliferation." (PMID 28572530, 2017). "Despite the fact that only a subset of patients with osteosarcoma are sensitive to IGF-1R inhibition, the strong preclinical rationale deserves further clinical and translational exploration." (PMID 26563243, 2016). "al described the relevance of insulin receptor isoform A (IR-A) and hybrid-receptors (HR), which consist of one α and one β subunit IR heterodimer and one α and one β subunit IGF1R heterodimer in osteosarcoma samples." (PMID 25170759, 2014). "Using real-time quantitative PCR, we evaluated the expression of miR-194 and two miR-194 target genes, CDH2 and IGF1R in osteosarcoma samples from 107 patients and 99 formalin- or paraformalin-fixed paraffin-embedded tissues." (PMID 25096247, 2014). "We then examined IGF1R and N-cadherin protein expression in 99 paraffin specimens of osteosarcoma using immunohistochemistry analysis." (PMID 25096247, 2014). "We examined IGF1R and N-cadherin protein expression in 107 patients with osteosarcoma using real-time quantitative PCR." (PMID 25096247, 2014). "Knockdown of IGF1R in osteosarcoma cell lines induces apoptosis, inhibits cell proliferation and enhances chemo- and radio-sensitivities by decreasing Bcl-2 expression and increasing Caspase-3 and Bax expression." (PMID 24391788, 2013).
osteosarcoma (continued). "This study provides an in vitro rationale for using dual IR/IGF1R inhibitors in preclinical studies of osteosarcoma." (PMID 23688189, 2013). "Most importantly, phosphorylated IRS-1, which is a measure for pathway activity, was detected in all four osteosarcoma cell lines, indicating that IGF1R signaling is active in osteosarcoma, and is possibly regulated upstream of IGF1R." (PMID 23688189, 2013). "This study provides an in vitro rationale for using IR/IGF1R inhibitors in preclinical studies of osteosarcoma." (PMID 23688189, 2013). "Specifically, upstream inhibitors of IGF1R signaling were found to be downregulated in osteosarcoma, and low expression of these genes correlated with worse event-free survival." (PMID 23688189, 2013). "More recently, two osteosarcoma cell lines were among the lineages that showed enhanced activity when exposed to both IGF-1R antibody with rapamycin." (PMID 23383402, 2013). "Nearly 20 years after that first observation, a mouse xenograft model using six different osteosarcoma cell lines demonstrated objective responses to R1507, a monoclonal anti-IGF1R antibody, in vivo." (PMID 23383402, 2013). "Evidence shows high expression of IGF1R contributes to osteosarcoma cell growth, invasion and migration, and is correlated with poor prognosis of OS patients." (PMID 24391788, 2013). "In a phase I study with the monoclonal antibody RG1507, an IGF-1R antagonist, patients with osteosarcoma showed a positive response to treatment with the antibody." (PMID 24216993, 2013). "Osteosarcoma cell lines are dependent on IGF-1 via IGF-1R for in vitro growth, and IGF-1R expression has been associated with poor prognosis." (PMID 23383402, 2013). "Increase of IGF-1R expression is correlated with tumor metastases and overall survival in patients with osteosarcoma." (PMID 24216993, 2013). "Treatment with OSI-906 resulted in inhibition of phosphorylation of IRS-1 Y612, a direct downstream target of IGF1R, and in strong inhibition of proliferation in 3 of 4 osteosarcoma cell lines." (PMID 23688189, 2013). "We thus expect clinical outcomes to improve for osteosarcoma patients treated with dual IGF1R/IR inhibitor OSI-906." (PMID 23688189, 2013). "Since most profound differences in mRNA expression were found at and upstream of the receptor of this pathway, we set out to inhibit IR/IGF1R using OSI-906, a dual inhibitor for IR/IGF1R, on four osteosarcoma cell lines." (PMID 23688189, 2013). "We have analyzed genome-wide gene expression in high-grade osteosarcoma cell lines and pretreatment biopsies, and observed significantly altered activity of genes involved in IGF1R signaling when compared to profiles of mesenchymal stem cells and osteoblasts." (PMID 23688189, 2013). "Over-expression of miR-133b in osteosarcoma cell lines U2-OS and MG-63 led to the inhibition of cell proliferation, migration, invasion through decreasing the expression of IGF1R, MET, phospho-Akt and FAK." (PMID 24391788, 2013). "Phosphorylation of IRS-1, a direct downstream target of IGF1R signaling, was inhibited in the responsive osteosarcoma cell lines." (PMID 23688189, 2013). "In conclusion, we have shown that IGF1R signaling is active in osteosarcoma, and that dual inhibition of IR/IGF1R inhibits downstream signaling and proliferation of these cells." (PMID 23688189, 2013). "There are several human monoclonal antibodies (mAbs) against IGF-1R available, and some of them have been or are currently being investigated in phase I/II clinical trials including patients with osteosarcoma." (PMID 24216993, 2013). "Because IGF1R signaling can be exploited as a therapeutic target, and osteosarcoma patients are in severe need of new therapies, we examined mRNA expression of members of this signaling pathway in detail." (PMID 23688189, 2013). "Using gene set analysis of genome-wide gene expression data of high-grade osteosarcoma biopsies and cell lines, we detected an over-representation of IGF1R signaling." (PMID 23688189, 2013).